POLR1D (RNA polymerase I and III subunit D)
Description:
DNA-dependent RNA polymerase catalyzes the transcription of DNA into RNA using the four ribonucleoside triphosphates as substrates. Common component of RNA polymerases I and III which synthesize ribosomal RNA precursors and short non-coding RNAs including 5S rRNA, snRNAs, tRNAs and miRNAs, respectively.
Synonyms: RPA16; RPAC2; RPO1-3; RPA9; MGC9850; AC19; RPC16; TCS2
Tractability: Small molecule: a structure with a bound ligand is known. PROTAC: ubiquitination databases record sites on it; its protein half-life has been measured.
Gene: Protein-coding gene on chromosome 13 (27,620,742 to 27,744,237, forward strand). Ensembl gene ENSG00000186184.
Subcellular location: Nucleus; Nucleus, nucleolus
Subcellular location (Human Protein Atlas): Golgi apparatus; Nucleoplasm
Pathways (Reactome):
Gene expression (Transcription): B-WICH complex positively regulates rRNA expression; NoRC negatively regulates rRNA expression; RNA Polymerase I Promoter Escape; RNA Polymerase I Transcription Initiation; RNA Polymerase I Transcription Termination; RNA Polymerase III Abortive And Retractive Initiation; RNA Polymerase III Chain Elongation; RNA Polymerase III Transcription Initiation From Type 1 Promoter; RNA Polymerase III Transcription Initiation From Type 2 Promoter; RNA Polymerase III Transcription Initiation From Type 3 Promoter; RNA Polymerase III Transcription Termination
Immune System: Cytosolic sensors of pathogen-associated DNA
Gene Ontology:
Molecular function: protein binding; DNA-directed RNA polymerase activity; DNA binding; protein dimerization activity
Biological process: termination of RNA polymerase III transcription; transcription by RNA polymerase III; transcription elongation by RNA polymerase I; transcription initiation at RNA polymerase III promoter; nucleolar large rRNA transcription by RNA polymerase I; termination of RNA polymerase I transcription; transcription initiation at RNA polymerase I promoter; DNA-templated transcription
Cellular component: nucleus; RNA polymerase I complex; RNA polymerase III complex; intracellular protein-containing complex; nucleolus
Genetic constraint (gnomAD): Loss-of-function variants: 7 observed, 7.81 expected, observed/expected ratio (o/e) 0.9, 90% interval 0.51 to 1.63. That is too few expected variants to judge how well the gene tolerates losing a copy. Missense variants: 128 observed, 140.17 expected, observed/expected ratio (o/e) 0.91, 90% interval 0.79 to 1.06. Synonymous variants: 45 observed, 50.79 expected, observed/expected ratio (o/e) 0.89, 90% interval 0.7 to 1.14.
Gene-disease validity (ClinGen):
ClinGen rates the evidence that POLR1D causes each of these diseases.
Treacher Collins syndrome 2 (autosomal dominant): Definitive.
Homologues: Orthologues: chimpanzee POLR1D (100% identical), pig POLR1D (95% identical), mouse Polr1d (90% identical), rat Polr1d (90% identical), zebrafish polr1d (53% identical), guinea pig POLR1D (46% identical), tropical clawed frog polr1d.2 (43% identical), Drosophila melanogaster Polr1D (30% identical), Caenorhabditis elegans rpac-19 (27% identical). Paralogues in human: POLR2J (26% identical), POLR2J2 (24% identical), POLR2J3 (24% identical).
Diseases named in the same sentence as POLR1D in open-access papers:
POLR1D is named in the same sentence as 35 diseases in open-access papers, as found by Europe PMC text mining. Sharing a sentence is not in itself a finding about the gene and the disease. The quoted sentences say what the papers report.
Treacher-Collins syndrome (11 papers, 2013 to 2025). A congenital disorder of craniofacial development characterized by bilateral symmetrical oto-mandibular dysplasia without abnormalities of the extremities, and associated with several head and neck defects. "For instance, pathogenic variants in two subunits of RNA polymerase III, POLR1C and POLR1D, were previously linked to Treacher-Collins syndrome (MIM#248390, #613717)." (PMID 40229899, 2025). "In yeast, Treacher Collins syndrome-related mutations in POLR1D result in altered functions of both RNA pol I and III." (PMID 35611941, 2022). "Transcription of the ribosomal RNAs (rRNAs) by RNA polymerases (Pol) I and III, is considered a rate limiting step of ribosome biogenesis and mutations in the genes coding for RNA Pol I and III subunits, POLR1C and POLR1D cause Treacher Collins syndrome, a rare congenital craniofacial disorder." (PMID 27448281, 2016). "Furthermore, we have established polr1c and polr1d mutant zebrafish as models of Treacher Collins syndrome together with a unifying mechanism underlying its pathogenesis and possible prevention." (PMID 27448281, 2016). "More specifically, mutations in POLR1A cause Acrofacial Dysostosis Cincinnati type (AFDCin), whereas mutations in POLR1B, POLR1C and POLR1D and the Pol I associated protein, TCOF1/TREACLE lead to Treacher Collins Syndrome (TCS)." (PMID 37639467, 2023). "For example, Treacher Collins syndrome is caused by mutations in POLR1C, POLR1D, or TCOF1, which affect rDNA transcription by RNA pol I and ribosome biogenesis." (PMID 35611941, 2022). "Pathogenic variants in the TCOF1 but also the POLR1D and POLR1C genes have been previously associated with Treacher Collins syndrome (TCS) types 1–3, respectively." (PMID 33262786, 2020). "Consistent with this pattern of activity, polr1c and polr1d homozygous mutant zebrafish exhibit cartilage hypoplasia and cranioskeletal anomalies characteristic of humans with Treacher Collins syndrome." (PMID 27448281, 2016). "Treacher Collins syndrome is associated with mutations of POLR1C and POLR1D (OMIM 248390 and OMIM 613717), and hypomyelinating leukodystrophy is associated with mutations of POLR3A and POLR3B (OMIM 607694 and OMIM 614381)." (PMID 24040563, 2013). "Mutations in genes encoding the two RNA Pol I subunits, POLR1C and POLR1D, and in the nucleolar protein Treacher Collins-Franceschetti syndrome 1 (TCOF1, also known as treacle) cause the craniofacial disorder, Treacher Collins syndrome (OMIM 248390, OMIM 613717 and OMIM 154500)." (PMID 24040563, 2013). "The identification of causative mutations in the TCOF1 gene (85% of the cases), but also in the RNA polymerase I (Pol I) subunits POLR1C, POLR1D and recently, POLR1B strongly suggests that perturbation of ribosome biogenesis is the underlying cause of Treacher Collins Syndrome." (PMID 35646927, 2022). "Treacher Collins Syndrome (TCS) (or Franceschetti Syndrome in other words) is a rare congenital deformity with a strong genetic background—with four genes being responsible (TCOF1, POLR1D, POLR1C and POLR1B)." (PMID 40649114, 2025). "The genetic link of Treacle, POLR1C, POLR1D, and POLR1B to Treacher Collins Syndrome (TCS) in humans strongly indicates that disturbance of ribosome biogenesis is linked to the development of the disease." (PMID 35646927, 2022). "Notably, several genes involved in the craniofacial-biased disease Treacher Collins syndrome, TCOF1, POLR1C, and POLR1D, were low-scoring genes found to be expressed at high levels in virtually all tissues (Gini scores 0.23, 0.19, and 0.15 respectively)." (PMID 37532691, 2023).
colorectal cancer (5 papers, 2013 to 2025). A primary or metastatic malignant neoplasm that affects the colon or rectum. "POLR1D expression was increased in colorectal cancer samples and implicated in cancer occurrence, progression, and resistance." (PMID 40650119, 2025). "POLR1D has been reported to be associated with the promotion of colorectal cancer progression and prediction of poor prognosis of patients." (PMID 32285560, 2020). "Camps et. al. identified that loss of POLR1D function affects cell viability in colorectal cancers." (PMID 24088394, 2013). "The genes in the reported colorectal cancer group include POLR1D, DGKB, SULT2B1 SMPD1 GOT2, MTHFD1L and ACADM." (PMID 32285560, 2020). "Additionally, POLR1D has been observed to influence the expression of VEGF-α and EREG, resulting in acquired resistance to bevacizumab in colorectal cancer." (PMID 38256104, 2024).
leukodystrophy (3 papers, 2016 to 2021). Leukodystrophies are a group of rare, progressive, metabolic, genetic diseases that affect the brain, spinal cord and often the peripheral nerves. "However, similar to POLR1C, recessive mutations in POLR1D have also been identified in association with TCS, but to date none of these have been linked to leukodystrophy." (PMID 27448281, 2016).
lung carcinoma (2 papers, 2024 to 2025). "Lung cancer cell loss-of-function tests showed that POLR1D silencing could attenuate cell viability both in SK-MES-1 and in H2170 cells." (PMID 38844975, 2024). "Silencing of POLR1D in lung cancer cells SK-MES-1 and H2170 inhibited proliferation." (PMID 40650119, 2025).
breast carcinoma (1 paper, 2022). "Additionally, we observed downregulation of genes such as POLR1A, POLR1D, POLR1E, TAF1B, LAMP1, and CDKN1A in response to AQ treatment demonstrating the role of AQ in regulating RNA polymerase subunits and effect on overall gene transcription in breast cancer." (PMID 36232751, 2022).
microphthalmia (1 paper, 2016). Congenital or developmental anomaly in which the eyeballs are abnormally small. "Although overall body size is comparable between mutant embryos and control siblings, polr1c-/- and polr1d-/- mutants present with a considerably smaller head together with mandibular hypoplasia and microphthalmia." (PMID 27448281, 2016).
cancer (6 papers, 2013 to 2025). A tumor composed of atypical neoplastic, often pleomorphic cells that invade other tissues. "RNA polymerase I subunit D (POLR1D), encoding a subunit of both RNA polymerase I and III, has been shown to be overexpressed in several human cancer types." (PMID 38273073, 2024). "The RNA polymerase I subunit D (POLR1D) gene can induce various cancers." (PMID 38844975, 2024). "A current study reported that POLR1D plays a vital role in cancer prognosis." (PMID 38844975, 2024). "Furthermore, the inhibitory effects of knocking down ADM and POLR1D expression on cancer-related biological behaviors in CAL-27 and SAS cells were experimentally validated." (PMID 38256104, 2024). "In summary, our results suggest that POLR1D may act as a potential driver gene in the 13q12.2 amplification and may affect cancer progression by increasing the expression of VEGFA and EREG." (PMID 32087735, 2020). "ELOVL7, PTDSS1, POLR1D, TBC1D22A, CCNC and TCF25 are some of the interesting genes with cancer related functions identified from the DES analysis." (PMID 24088394, 2013). "Despite a recent report describing the frequent overexpression of POLR1D in CRC, a role of POLR1D in cancer has not otherwise been thoroughly described in the literature." (PMID 32087735, 2020).
tumor (2 papers, 2024 to 2025). "It has been reported that POLR1D was positively correlated to tumor size and poor survival of CRC patients." (PMID 38273073, 2024). "Aberrant expression of POLR1D significantly promoted cell proliferation and migration in vitro, and influenced tumor growth in vivo." (PMID 38273073, 2024). "In our study, we also found that POLR1D was highly expressed in the high tumor budding group." (PMID 38273073, 2024). "These suggested that POLR1D may function as a risk factor for predicting the outcome of CRC patients, but the relationship between POLR1D and tumor budding needs to be further explored." (PMID 38273073, 2024).
POLR1D also shares sentences with these, for which no sentence is quoted: acrofacial dysostosis (1 paper); acrofacial dysostosis Cincinnati type (1); alcoholic liver diseases (1); Anxiety (1); Arthritis (1); benign tumors (1); branchiootic syndrome 1 (1); cartilage-hair hypoplasia (1); choanal atresia (1); chronic kidney disease (1); cystic kidney disease (1); Diamond-Blackfan anemia (1); fibrosis (1); glioma (1); hamartoma (1); heart failure (1); infection (1); mandibulofacial dysostosis (1); mastitis (1); microtia (1); Obesity (1); protein folding disorders (1); sarcoidosis (1); Shwachman-Diamond syndrome (1); Tuberous Sclerosis Complex (1); type 2 diabetes (1); X-linked dyskeratosis congenita (1).